RHCE (Rh blood group CcEe antigens)
Description:
Component of the ankyrin-1 complex, a multiprotein complex involved in the stability and shape of the erythrocyte membrane. Mediates the primary membrane attachment site for ANK1 when associated with RHAG. May participate in the ammonium and carbon dioxide transport through the heterotrimer form (Probable).
Synonyms: RhPI; CD240CE; RHC; RHE; SLC42A4; RH; RH30A; RHCe(152N); RHIXB; RHNA; Rh4; RhIVb(J); RhVI; RhVIII
Tractability: Small molecule: a structure with a bound ligand is known. Antibody: its Gene Ontology location is reachable by antibodies, with high confidence; UniProt predicts a signal peptide or a membrane-spanning region.
Gene: Protein-coding gene on chromosome 1 (25,362,249 to 25,430,192, reverse strand). Ensembl gene ENSG00000188672.
Subcellular location: Membrane
Subcellular location (Human Protein Atlas): Nucleoplasm; Plasma membrane
Pathways (Reactome):
Metabolism: Rhesus blood group biosynthesis
Gene Ontology:
Molecular function: ammonium channel activity
Biological process: ammonium homeostasis; ammonium transmembrane transport
Cellular component: ankyrin-1 complex; plasma membrane; membrane
Genetic constraint (gnomAD): Loss-of-function variants: 19 observed, 40.54 expected, observed/expected ratio (o/e) 0.47, 90% interval 0.33 to 0.69. The synonymous counts are far from expectation, so gnomAD's model fits this gene poorly and the ratio says little. Missense variants: 377 observed, 507.74 expected, observed/expected ratio (o/e) 0.74, 90% interval 0.68 to 0.81. Synonymous variants: 155 observed, 205.97 expected, observed/expected ratio (o/e) 0.75, 90% interval 0.66 to 0.86.
Homologues: Orthologues: macaque RHCE (78% identical), dog RHCE (61% identical), pig RHCE (61% identical), mouse Rhd (57% identical), rat Rhd (55% identical), tropical clawed frog rhd (35% identical), zebrafish rhd (34% identical), Drosophila melanogaster Rh50 (29% identical), Caenorhabditis elegans rhr-1 (28% identical), Caenorhabditis elegans rhr-2 (26% identical). Paralogues in human: RHD (91% identical), RHAG (35% identical), RHBG (32% identical), RHCG (32% identical).
Diseases named in the same sentence as RHCE in open-access papers:
RHCE is named in the same sentence as 8 diseases in open-access papers, as found by Europe PMC text mining. Sharing a sentence is not in itself a finding about the gene and the disease.
RHCE shares sentences with these, for which no sentence is quoted: melanoma (2 papers); cancer (1); cholangiocarcinoma (1); COVID-19 (1); hyperlipidemia (1); paraganglioma (1); pheochromocytoma (1); prostate adenocarcinoma (1).